PMM2 (phosphomannomutase 2)
Diseases named in the same sentence as PMM2 in open-access papers (continued):
Sharing a sentence is not in itself a finding about the gene and the disease.
glycosylation disorder (6 papers, 2019 to 2025). "The most commonly widespread glycosylation disorder is manifested through phosphomannomutase 2 (PMM2) mutation, which transforms mannose-6-phosphate to mannose-1-phosphate." (PMID 35159390, 2022). "Caused by a defect in the enzyme phosphomannomutase 2 (EC: 5.4.2.8), this disturbance of mannose metabolism is an archetypical glycosylation disorder and remains the most common one, with approximately 1,000 cases diagnosed to date." (PMID 34567084, 2021). "PMM2-CDG was the first glycosylation disorder and was characterized in the 1980s by the Belgian Pediatrician Jaak Jaeken." (PMID 34567084, 2021). "As expected, this mutant had reduced PMM-2 enzymatic activity; by contrast, PMM-2 enzymatic activity was unchanged in a png-1 homozygous null mutant and model of NGLY1 deficiency (another glycosylation disorder) and in wild-type N2 worms." (PMID 31636082, 2019).
hyperinsulinemic hypoglycemia (6 papers, 2019 to 2025). An inherited autosomal recessive syndrome characterized by the disorganized formation of new islets in the pancreas and congenital hyperinsulinism. "In this context another interesting differential diagnosis of ARPKD are variants in the promoter region of PMM2 encoding Phosphomannomutase 2 that can result in an ARPKD-like kidney phenotype combined with hyperinsulinemic hypoglycemia." (PMID 34676227, 2021). "Recessive mutations in PMM2 were reported as associated to hyperinsulinemic hypoglycemia (HI) and PKD." (PMID 32457805, 2020).
hyperinsulinism (6 papers, 2020 to 2023). Abnormally high levels of insulin in the blood. "The entities reported to be associated with hyperinsulinism are PMM2-CDG (CDG1a), MPI-CDG (CDG1b), ALG3-CDG (CDG1d), and PGM1-CDG (CDG1t) (reviewed by 97, 98)." (PMID 37065762, 2023). "A distinct clinical syndrome of hyperinsulinism and autosomal recessive polycystic kidney disease (HIPKD) arises in the context of a specific variant in the PMM2 promotor, either in homozygosity, or compound heterozygous with a deleterious PMM2 variant." (PMID 36773065, 2023). "We searched PubMed for full-text original studies and case reports written in English, to identify reports about the genetic pathogenesis, diagnosis, and management pathophysiology, consequences, and treatment of phosphomannomutase 2 hyperinsulinemia." (PMID 36726472, 2022). "The search terms used were “hyperinsulinism”, “congenital hyperinsulinism”, “congenital hypoglycemia”, “phosphomannomutase 2”, and “PMM2 protein”." (PMID 36726472, 2022). "Phosphomannomutase 2 hyperinsulinemia (PMM2-HI) is an extremely rare subtype which is first reported in 2017, with only 18 families reported so far." (PMID 36726472, 2022). "Consequently, this results in abnormal insulin secretion from pancreatic β-cells and phosphomannomutase 2 hyperinsulinism (PMM2-HI)." (PMID 36726472, 2022). "However, this is also the case with the other key manifestations of hyperinsulinism and cystic kidney disease, both of which are ubiquitous in currently described PMM2-HIPKD cases but rare in PMM2-CGD (1%, and 2% of cases, respectively)." (PMID 36773065, 2023).
Stroke (6 papers, 2014 to 2025). Sudden impairment of blood flow to a part of the brain due to occlusion or rupture of an artery to the brain. "Among these, three are likely monogenic causes of stroke (ELN, SCN5A, and VHL genes), two are considered risk factors (FV and ADAMTS13), two have conflicting interpretations (ACAD9 and ENG), and three are most likely benign (CBS, PMM2, and PKD1)." (PMID 40650005, 2025). "Previous studies have suggested that impairment of the collagen IV network contributes to PMM2-CDG-related symptoms, such as intra-cerebral hemorrhage and stroke-like episodes." (PMID 38436559, 2024). "PMM2-CDG patients present with a wide range of clinical features, including hypotonia, global developmental delay, seizures, stroke-like episodes, liver disease, and endocrine and hematologic abnormalities." (PMID 37628636, 2023). "Our sample confirms that stroke-like episodes do not seem to correspond to the adult phenotype of PMM2-CDG." (PMID 25497157, 2014).
Intellectual disability (4 papers, 2014 to 2025). "Severe intellectual disability, peripheral neuropathy, and severe PMM2 variants were all significantly associated with worse functional outcome." (PMID 33619652, 2021). "PMM2-CDG is a multisystem disease with a broad neurological phenotype including cerebellar hypotrophy/atrophy, psychomotor delay/intellectual disability, acquired microcephaly, strabismus and retinopathy, epilepsy, stroke-like episodes and peripheral neuropathy." (PMID 33619652, 2021).
retinitis pigmentosa (4 papers, 2014 to 2024). Retinitis pigmentosa (RP) is an inherited retinal dystrophy leading to progressive loss of the photoreceptors and retinal pigment epithelium and resulting in blindness usually after several decades. "Two siblings with a shared genotype (PMM2, p.R141H in 1 allele and the noncoding variant c.640-23A>G in the second allele) had retinitis pigmentosa and sensorineural hearing loss (samples 27 and 28)." (PMID 38587076, 2024).
autosomal recessive polycystic kidney disease (3 papers, 2022 to 2023). An inherited disorder characterized by the development of cysts affecting the collecting ducts. "Case Summary: Here, we describe a pair of siblings with HH associated with autosomal recessive polycystic kidney disease (ARPKD) and PMM2 mutation." (PMID 36412659, 2022).
Failure to thrive (3 papers, 2018 to 2025). Failure to thrive (FTT) refers to a child whose physical growth is substantially below the norm. "Although growth failure, as well as failure to thrive and acquired microcephaly, are commonly reported in patients with PMM2-CDG, this study provides a unique analysis of longitudinal data on the anthropometric phenotype and genetic correlations in a group of Polish PMM2-CDG patients." (PMID 34682117, 2021).
galactosemia (3 papers, 2021 to 2023). "AT-007 from Applied Therapeutics has received Orphan Drug and Pediatric Rare Disease designations from the FDA to treat SORD deficiency, Galactosemia, and phosphomannomutase-2 deficiency, a congenital disorder of glycosylation (PMM2-CDG) featured by increased sorbitol level." (PMID 37014713, 2023). "Impaired polyol metabolism and intracellular polyol accumulation have been implicated in many chronic diseases, including diabetic complications, such as diabetic peripheral neuropathy and retinopathy, and metabolic disorders, such as Galactosemia and PMM2-CDG." (PMID 37014713, 2023).
Hypoglycemia (3 papers, 2020 to 2022). A decreased concentration of glucose in the blood. "We conducted a systematic review of the literature on genetically and/or biochemically confirmed PMM2‐CDG patients who developed hypoglycemia." (PMID 32071842, 2020). "This review will illustrate the recent advances in genetic pathogenesis, diagnosis, and management regarding PMM2-HI, in an attempt to contribute to clinicians’ awareness of the disease, which in turn will facilitate the early diagnosis and management of hypoglycemia in infancy and childhood." (PMID 36726472, 2022).
virus infection (3 papers, 2013 to 2020). "We studied twelve patients with different clinical severity and different pmm2 mutations, three of them suffered from severe viral infections during their first year of life." (PMID 27415628, 2016). "Interestingly, differential regulation of PMM2 has been associated with virus infection of chicken embryo fibroblast cell cultures, thus providing an additional line of evidence supporting PMM2 down-regulation in our study." (PMID 23521892, 2013). "However, PMM2-CDG participants (27.7%, n = 18/65) identified virus infections more frequently than controls (18.9%, n = 10/53)." (PMID 32635232, 2020).
ciliopathies (2 papers, 2022 to 2024). "In 4 of them, the cause of the genetic disease was pathogenic variants related with ciliary function (2 confirmed cases, 2 suspected), such as PMM2 and HNF1B, carrying overlapped phenotypes with ciliopathies." (PMID 35401179, 2022).
cystic kidney disease (2 papers, 2022 to 2023). A congenital or acquired kidney disorder characterized by the presence of renal cysts. "Renal involvement in PMM2-CDG manifests as cystic kidney disease, echogenic kidneys, nephrotic syndrome or mild proteinuria." (PMID 36412659, 2022).
familial hemiplegic migraine (2 papers, 2018 to 2021). A migraine disorder characterized by individual and family history of aura that includes motor weakness. "This is the case of PMM2-CDG and some channelopathies related to CACNA1A, ATP1A2, and SCN1A mutations, leading to episodes called familial hemiplegic migraine (FHM)." (PMID 34708008, 2021). "Stroke-like episodes (SLE) occur in phosphomannomutase deficiency (PMM2-CDG), and may complicate the course of channelopathies related to Familial Hemiplegic Migraine (FHM) caused by mutations in CACNA1A (encoding CaV2.1 channel)." (PMID 29470411, 2018).
hypogonadism (2 papers, 2019 to 2025). A disorder characterized by decreased function of the gonads. "Phosphomannomutase 2 deficiency (PMM2-CDG) may also lead to hypogonadism, as glycosylation is crucial for both spermatogenesis and oogenesis." (PMID 41480351, 2025).
liver disease (2 papers, 2021). "The authors classified CDG based on liver involvement into two main groups: one with predominant/isolated liver involvement (MPI-CDG, CCDC115-CDG, TMEM199-CDG, ATP6AP1-CDG) and the other associated with liver disease (PMM2-CDG, ALG1-CDG, ALG3-CDG, ALG8-CDG, ALG9-CDG, PGM1-CDG)." (PMID 34291020, 2021). "In our cohort, the predominant liver phenotype was observed in MPI-CDG patients, while other CDG like PMM2-CDG, ATP6AP1-CDG were associated with liver disease." (PMID 33407696, 2021).
liver dysfunction (2 papers, 2022 to 2024). "Human tissues tested showed the highest expression of PMM2 in the pancreas and liver, and patients with PMM2 deficiency (PMM2-CDG, congenital disorders of glycosylation) have a broad and variable spectrum of clinical presentations with liver dysfunction." (PMID 36291201, 2022).
renal cell carcinoma (2 papers, 2023 to 2024). "Consistent with our findings, knockdown of PMM2 in renal cell carcinoma cells inhibited cancer cell migration and invasion, indicating that overexpression of PMM2 could promote malignancy." (PMID 38576019, 2024). "Studies have indicated that the overexpression of PMM2 could promote malignancy of renal cell carcinoma." (PMID 37428395, 2023).
renal failure (2 papers, 2016 to 2022). "In this patient, kidney failure was precipitated by sepsis physiology, and the contribution of underlying PMM2‐deficiency to progression of ESRD is uncertain." (PMID 35281664, 2022). "Patient 1 appeared to develop renal failure because of her underlying PMM2‐deficiency." (PMID 35281664, 2022).
Thrombocytopenia (2 papers, 2022 to 2025). A reduction in the number of circulating thrombocytes. "Notably, thrombocytopenia has also been described in various other types of CDG, including ALG1-, ALG8-, GALE-, GNE-, MPI-, PMM2-, and B4GALT1-CDG." (PMID 40613041, 2025).
angioedema (1 paper, 2020). Swelling involving the deep dermis, subcutaneous, or submucosal tissues, representing localized edema. "However, we must remember that most PMM2-CDG patients have not been exposed to the triggering factors that cause angioedema in carriers of the p.Thr309Lys mutation (pregnancy, oral contraceptives...), and on the other hand that marked edemas were already reported in CDG patients." (PMID 33036649, 2020). "PMM2-CDG have high levels of FXII lacking N-glycosylation at Asn414, but this glycoform displays similar activation than fully glycosylated, explaining the absence of angioedema in CDG." (PMID 33036649, 2020).
autoimmune disease (1 paper, 2020). A disorder resulting from loss of function or tissue destruction of an organ or multiple organs, arising from humoral or cellular immune responses of the individual to their own tissue constituents. "Besides PMM2-CDG, three reports of autoimmune diseases have been associated with the ALG gene family (eosinophilic esophagitis in an ALG1-CDG patient with a severe phenotype, and psoriasis in an ALG3-CDG and an ALG6-CDG patient)." (PMID 32635232, 2020).
channelopathies (1 paper, 2018). "Acute and chronic phenotypes of patients with PMM2-CDG or CACNA1A channelopathies show similarities." (PMID 29470411, 2018). "As for PMM2-CDG, the pathogenesis of SLE in channelopathies is still not fully understood." (PMID 29470411, 2018).
Cirrhosis (1 paper, 2021). A chronic disorder of the liver in which liver tissue becomes scarred and is partially replaced by regenerative nodules and fibrotic tissue resulting in loss of liver function. "However, liver fibrosis, or even cirrhosis, was reported in PMM2-CDG, TMEM199-CDG, and NGLY1-CDDG." (PMID 34291020, 2021).
coloboma (1 paper, 2021). An abnormality in which a part of a structure in one or both eyes is missing. "These include: connective tissue involvement in ATP6AP1-CDG, midline malformations in PGM1-CDG, chronic diarrhoea in MPI-CDG, inverted nipples and abnormal fat distribution in PMM2-CDG, cataract/coloboma in SRD5A3-CDG, cerebellar hypoplasia in PMM2-CDG and SRD5A3-CDG." (PMID 33407696, 2021).
colon cancer (1 paper, 2021). "qRT-PCR was performed from RNA extracted from 43 pairs of colon cancer and adjacent normal tissues to observe the relative expression levels of eight GRGs (P4HA1, STC2, CHPF2, PMM2, PGM2, ENO3, PPARGC1A, and PPP2CB)." (PMID 34422808, 2021).
cystic kidneys (1 paper, 2022). "PMM2 mutation leading to abnormal glycosylation and causing cystic kidneys and the alteration of insulin secretion is the most likely pathogenesis of this clinical spectrum." (PMID 36412659, 2022).
depression (1 paper, 2022). "Among them, except for PGM1, PMM2, and INMT, the expression of the other 7 proteins were significantly upregulated in susceptible mice, suggesting the potential role of these molecules in the pathogenesis of CSDS-induced depression in mice." (PMID 36291201, 2022). "However, further study is warranted to discover the pathophysiological role of dysregulation of PMM2 in CSDS-induced depression." (PMID 36291201, 2022).
dystroglycanopathies (1 paper, 2021). "The cerebellum is commonly affected in PMM2-CDG, dystroglycanopathies, and SRD5A3-CDG, while the course of cerebellar ataxia is not progressive." (PMID 34540767, 2021).
eczema (1 paper, 2020). "Among non-PMM2-CDG, skin allergies—particularly eczema—were the most reported, especially in ALG13-, SRD5A3- and PIGA-CDG." (PMID 32635232, 2020).
Friedreich ataxia (1 paper, 2015). An inherited condition that affects the nervous system and causes movement problems. "Moreover, unlike Friedreich ataxia, spinal cord abnormalities are not included in the PMM2-CDG phenotype." (PMID 26502900, 2015).
gastroenteritis (1 paper, 2022). An inflammatory disorder that affects the upper and lower gastrointestinal tract. "Given that both patients 1 and 2 developed AKI while receiving treatment for gastroenteritis and pneumonia, respectively, we hypothesize that compromised immune function characteristic of PMM2‐CDG may have played a role in exacerbating the progression of kidney disease." (PMID 35281664, 2022).
generalized epilepsy (1 paper, 2021). Epilepsy that is characterized by generalized seizure types and may have typical interictal and/or ictal EEG findings that accompany generalized seizure types (for example generalized spike-wave). "Generalized epilepsy, myoclonic fits and/or partial seizures have been reported from 15 to 47.8% of patients with PMM2-CDG especially in those more severely affected supporting the association with a worst functional outcome." (PMID 33619652, 2021).
GNE myopathy (1 paper, 2023). "This happened, for example, for acetazolamide (for PMM2-CDG, NCT04679389), oral GlcNAc Supplementation (for NGLY1 deficiency, NCT05402345), ManNAc (for GNE myopathy, NCT04231266), AVTX-803 (for Leukocyte Adhesion Deficiency type II, NCT05462587O)." (PMID 37644541, 2023).
hearing loss (1 paper, 2021). "Specifically, biallelic mutations were detected (i) in the PIGG gene in an 11-year-old male with ASD Asperger-type; (ii) in the PMM2 gene in a 14-year-old female with ASD, hearing loss, and ptosis; and (iii) in the CEP290 gene in a 13-year-old male with ID and attention deficit." (PMID 33921431, 2021).
hydrops fetalis (1 paper, 2015). Hydrops fetalis is a severe and challenging fetal condition usually defined as the excessive accumulation of fetal fluid within the fetal extravascular compartments and body cavities that manifests as edema, pleural and pericardial effusion and ascites. "Hydrops fetalis has also been described in PMM2-CDG and ALG1-CDG." (PMID 26066342, 2015).
hypergonadotrophic hypogonadism (1 paper, 2025). "As a result, endocrinopathies are frequently part of the clinical spectrum of PMM2-CDG, particularly hypergonadotrophic hypogonadism and pubertal abnormalities in female patients." (PMID 40771275, 2025).
inflammatory bowel disease (1 paper, 2023). A spectrum of small and large bowel inflammatory diseases of unknown etiology. "In summary, PMM2-HIPKD, arising consequent to variants in PMM2, is associated with early-onset inflammatory bowel disease and distinctive gastric pathology." (PMID 36773065, 2023).
Lafora disease (1 paper, 2021). Lafora disease (LD) is a rare, inherited, severe, progressive myoclonic epilepsy characterized by myoclonus and/or generalized seizures, visual hallucinations (partial occipital seizures), and progressive neurological decline. "We use the package to confirm existing knowledge related to immune cell-infiltration in Lafora disease and calcium channel involvement in PMM2-CDG, and suggest related genes for further study." (PMID 34301987, 2021).
melanoma (1 paper, 2011). A malignant, usually aggressive tumor composed of atypical, neoplastic melanocytes. "Surprisingly, melanoma cells were almost undetectable in PMM2." (PMID 22216160, 2011). "The tumor size in the P. acnes-treated melanoma-bearing mice, PMM1 and PMM2, was significantly smaller than in the control mice." (PMID 22216160, 2011).
ovarian carcinoma (1 paper, 2011). A malignant neoplasm originating from the surface ovarian epithelium. "The upregulated genes encode for proteins associated with ovarian cancer metastasis [SERPINB2/PAI2], metabolic activities [IDI1, PMM2] and gene expression/transcription [PCGF6, ZNF267]." (PMID 22022533, 2011). "In HIO-80 cells, there was significant upregulation of genes encoding for proteins associated with ovarian cancer metastasis [SERPINB2/PAI2], metabolic activities [IDI1, PMM2] and gene expression/transcription [PCGF6, ZNF267]." (PMID 22022533, 2011).
Pontocerebellar atrophy (1 paper, 2021). Atrophy affecting the pons and the cerebellum. "Pontocerebellar hypoplasia (PCH) and (olivo)pontocerebellar atrophy have been described in PMM2-CDG, particularly in the more severely affected patients also at autopsy." (PMID 33619652, 2021).
schizophrenia (1 paper, 2024). A major psychotic disorder characterized by abnormalities in the perception or expression of reality. "Both HYLS1 and PMM2 have not been implicated in GWAS, but their neural-cardiac roles are relevant to schizophrenia." (PMID 38167462, 2024). "Integrating HC ELEs with GWAS and gene regulatory networks further helps pinpoint previously undescribed but functionally relevant genes for BMI (e.g., CDK5, HSD11B1) and schizophrenia (e.g., HYLS1, PMM2)." (PMID 38167462, 2024).
thrombosis (1 paper, 2013). "We were particularly interested to investigate whether a potential CD59 defect in erythrocytes of PMM2-CDG patients might contribute to their increased incidence of thrombosis." (PMID 24139637, 2013).
metabolic disorder (7 papers, 2018 to 2024). "This metabolic disorder is caused by the mutation in PMM2 gene encoding for phosphomannomutase 2 (PMM2, EC 5.4.2.8)." (PMID 32660097, 2020).